OR5M9 (olfactory receptor family 5 subfamily M member 9)
Description:
Odorant receptor.
Synonyms: OR11-190
Tractability: Antibody: UniProt places it where antibodies can reach, with medium confidence; UniProt predicts a signal peptide or a membrane-spanning region; its Gene Ontology location is reachable by antibodies, with medium confidence.
Gene: Protein-coding gene on chromosome 11 (56,462,469 to 56,463,401, reverse strand). Ensembl gene ENSG00000150269.
Subcellular location: Cell membrane
Pathways (Reactome):
Sensory Perception: Expression and translocation of olfactory receptors
Gene Ontology:
Molecular function: olfactory receptor activity; G protein-coupled receptor activity
Biological process: G protein-coupled receptor signaling pathway; sensory perception of smell; detection of chemical stimulus involved in sensory perception of smell
Cellular component: plasma membrane; membrane
Genetic constraint (gnomAD): Missense variants: 452 observed, 391.24 expected, observed/expected ratio (o/e) 1.16, 90% interval 1.07 to 1.25. Synonymous variants: 169 observed, 143.96 expected, observed/expected ratio (o/e) 1.17, 90% interval 1.03 to 1.33.
Homologues: Orthologues: chimpanzee OR5M9 (98% identical), macaque OR5M9 (95% identical), dog OR5M9 (93% identical), mouse Or5m9 (90% identical), rat Or5m9 (90% identical), mouse Or5m9b (89% identical). Paralogues in human: OR5M3 (76% identical), OR5M8 (66% identical), OR5M10 (57% identical), OR5M1 (57% identical), OR5M11 (54% identical), OR5B21 (50% identical), OR5AP2 (50% identical), OR5D18 (50% identical), OR8U3 (49% identical), OR5B12 (49% identical), OR5B3 (49% identical), OR5I1 (49% identical), and 84 more.